GNAO1 (G protein subunit alpha o1)
Diseases named in the same sentence as GNAO1 in open-access papers (continued):
Sharing a sentence is not in itself a finding about the gene and the disease.
hemochromatosis (1 paper, 2025). A disorder of iron metabolism characterized by a triad of HEMOSIDEROSIS; LIVER CIRRHOSIS; and DIABETES MELLITUS. "Whole exome sequencing identified a heterozygous de novo variant NM_020988.3: c.116_118dup; p.Leu39_Gly40insVal (L39_G40insV) in GNAO1, as well as two heterozygous variants in the HFE gene related to hemochromatosis." (PMID 41387899, 2025).
hyperkinesia (1 paper, 2022). "Effective disease‐specific therapies included dopaminergic agents for neurotransmitters disorders, ketogenic diet for glucose transporter deficiency, and deep brain stimulation for SGCE‐, KMT2B‐, and GNAO1‐related hyperkinesia." (PMID 36054588, 2022).
Laryngomalacia (1 paper, 2025). Laryngomalacia is a congenital abnormality of the laryngeal cartilage in which the cartilage is floppy and prolapses over the larynx during inspiration. "Laryngomalacia, characterized by hypotonic narrowing of the upper airways, emerged as a major contributor to stridor and upper airway dysfunction in GNAO1-RD patients." (PMID 41153036, 2025).
pneumonia (1 paper, 2025). An acute, acute and chronic, or chronic inflammation focally or diffusely affecting the lung parenchyma, caused by an infection in one or both of the lungs (by bacteria, viruses, fungi, or mycoplasma.). "Children diagnosed with PKAN, suspected neurotransmitter disease, SLC18A2, or GNAO1 were particularly noteworthy, as all had recurrent pneumonia." (PMID 40531829, 2025).
prostate carcinoma (1 paper, 2018). A carcinoma that arises from epithelial cells of the prostate gland. "Increased gene body methylation in prostate cancer correlating with decreased expression of mRNA and protein expression was identified on GNAO1, LGALS1, TNS1, and PPAP2B." (PMID 29563510, 2018).
renal tumors (1 paper, 2022). "In silico analysis showed that tRF-5b can regulate the activity of the NFIC, GNAO1 and HIPK2 proteins, which are associated with renal tumors." (PMID 35409004, 2022).
rhabdomyolysis (1 paper, 2022). Necrosis or disintegration of skeletal muscle often followed by myoglobinuria. "Our report highlights that pallidal DBS may be used as a life-saving treatment in an emergency context in patients with GNAO1-related dystonic storm abating also subsequent severe complications such as rhabdomyolysis and the rare occurrence of acute colitis." (PMID 35725943, 2022).
speech disorder (1 paper, 2025). A term referring to disorders characterized by the disruption of normal speech. "Here, we describe the clinical course of two patients with de novo heterozygous GNAO1 variants—p.Leu39_Gly40insVal and p.Thr327Lys—who exhibit severe speech disorder and ID as prominent symptoms." (PMID 41387899, 2025). "Altogether, we described atypical GNAO1 mutations associated primarily with severe speech disorders and ID." (PMID 41387899, 2025). "Here, we describe two unrelated patients carrying novel GNAO1 mutations, with severe speech disorder manifesting as a prominent symptom." (PMID 41387899, 2025). "Our results broaden the clinical and mechanistic spectrum of GNAO1-related disorders, showing that severe speech disorders and ID can occur as defining features even in the absence of seizures or movement disorders." (PMID 41387899, 2025). "These rare findings are based on a limited number of cases and require confirmation in additional patients to establish firmer genotype–phenotype correlations for GNAO1-related severe speech disorders." (PMID 41387899, 2025). "However, it is worth noting the shared neurodevelopmental programs controlled by GNAO1 and FOXP2, the most studied monogenic cause of severe speech disorders." (PMID 41387899, 2025). "Additional cases will be needed to confirm whether the pattern observed here—severe speech disorder and ID with minimal or absent seizures and movement abnormalities—represents a distinct clinical subgroup within the GNAO1 spectrum." (PMID 41387899, 2025).
movement disorder (39 papers, 2016 to 2026). "The potentially uncertain underlying factors contributing to GNAO1-related movement disorders can be elucidated by examining GNAO1 signaling." (PMID 40771566, 2025). "A second theoretical foundation for GNAO1-associated movement disorders pertains to Gαo’s involvement in governing neurotransmitter release." (PMID 40771566, 2025). "Subsequently, additional patients emerged presenting a movement disorder-predominant phenotype linked to a subset of recurrent GNAO1 mutations." (PMID 40745211, 2025). "One of our findings is that only endogenous Gnao1 alterations in SCs affect re-myelination after PNI, whereas changes of Gnao1 in neurons do not, which actually surprised us because of some studies about Gnao1 mutations resulting in movement disorders." (PMID 38331815, 2024). "GNAO1-related disorders (GNAO1-RD) encompass a diverse spectrum of neurodevelopmental and movement disorders arising from variants in the GNAO1 gene." (PMID 38903163, 2024). "GNAO1-related disorder (GNAO1-RD) is a rare neurodevelopmental and movement disorder caused by pathogenic variants in the GNAO1 gene, encoding a G protein subunit crucial for neuronal signaling." (PMID 38903163, 2024). "GNAO1-RD represents a range of neurodevelopmental and movement disorders arising from pathogenic variants in the GNAO1 gene." (PMID 38903163, 2024). "GNAO1 loss of function variants was associated with epileptic encephalopathy, while gain of function variants was related to those causing predominantly movement disorders." (PMID 29948482, 2018). "Within this framework, GNAO1-associated movement disorders could arise from disruptions in either or both processes." (PMID 40771566, 2025). "Goldstein and Mercimek-Mahmutoglu reported that Gnao1-related movement disorder was associated with to the presynaptic role of Gαo (Gnao1-encoded G protein) in regulating the release of neurotransmitters including the dopamine, epinephrine, noradrenaline and 5-hydroxytryptamine, etc.." (PMID 38331815, 2024). "Movement disorder with onset during infancy or childhood (1 neonatal onset, 50 infantile onset, 13 childhood onset,) represents the core symptom (92 patients, 83% of cases) in patients with GNAO1 variants." (PMID 36003298, 2022). "The dystonic epochs and coordination deficits observed in KCTD5 KO reflect hyperkinetic movement disorder pathology observed in patients with polymorphisms in signal transduction machinery, including DRD2, GNAL, GNAO1, and GNB1." (PMID 40233107, 2025). "Pathogenic mutations in many of these genes (such as DRD2, GNAL, GNAO1, ADCY5, and PDE10A) have been identified in patients with movement disorders (such as dystonia and dyskinesia)." (PMID 40233107, 2025). "Order of drug selection for the acute management of dyskinetic crisis and basal movement disorder in GNAO1-RD." (PMID 38903163, 2024). "Individualized pharmacological recommendations for the chronic management of movement disorders in GNAO1-RD patients cannot be provided." (PMID 38903163, 2024). "The aim was to characterize the clinical and genetic features of patients with mild GNAO1‐related phenotype with prominent movement disorders." (PMID 35722775, 2022). "Differently from GNAO1 positive patients, the severity of movement disorders seems to decrease over disease course, giving way to an akinetic-rigid phenotype in late adolescence, and no episodic exacerbations have been reported [81••]." (PMID 29086067, 2017). "The movement disorder is present in almost 80% of individuals affected by the GNAO1-related disorder, and symptoms such as developmental delay, hypotonia, prominent chorea, and dystonia have been described in approximately 50% of cases with a typical age at onset of four." (PMID 38921008, 2024). "GNAO1 encephalopathy is mainly characterized by movement disorders (incidence > 80%)." (PMID 38921008, 2024). "We included patients diagnosed with GNAO1‐related movement disorders of delayed onset (>2 years)." (PMID 35722775, 2022).
movement disorder (continued). "Heterozygous KO mice (GNAO1+/−) showed no movement disorders such as those seen in the homozygous loss-of-function animals." (PMID 34685729, 2021). "Mutations in GNAO1 and other G-protein subunits (GNAL), adenylyl cyclase (ADCY5), and cyclic nucleotide phosphodiesterase (PDE10A) had been reported previously for early-onset movement disorders." (PMID 34122306, 2021). "Menke and colleagues further reported that de novo missense mutations in the GNAO1 codon 209 and 246 are predominantly associated with a movement disorder phenotype and developmental delay but without seizures." (PMID 29948482, 2018). "Here, we report a large cohort of patients with mild GNAO1‐related phenotypes, experiencing prominent movement disorders without severe chronic encephalopathy." (PMID 35722775, 2022). "We assumed that the roles of neuronal Gnao1 in movement disorders may be through additional non-myelination-related-mechanism, which was indeed supported by the following some studies." (PMID 38331815, 2024). "GNAO1 haploinsufficiency is often manifested as a very mild movement disorder with relatively late onset, which may explain the lack of an obvious linkage of nonsense variants to the development of NDD." (PMID 40225165, 2023).
neurodevelopmental disorder (19 papers, 2016 to 2026). A behavioral and cognitive disorder with onset during the developmental period that involves impaired or aberrant development of intellectual, motor, or social functions. "GNAO1-related neurodevelopmental disorders are caused by mutations in the GNAO1 gene encoding the major neuronal G protein, Gαo." (PMID 42024408, 2026). "Mutations in GNAO1, the gene encoding Gαo, are associated with a wide range of neurodevelopmental disorders." (PMID 41460161, 2026). "Background/Objectives: Pathogenic variants in GNAO1, encoding the inhibitory G protein subunit Gαo, cause severe neurodevelopmental disorders that remain largely refractory to pharmacological treatments." (PMID 42193465, 2026). "Among these, mutations in GNAO1, the gene encoding for Gαo, have been implicated in a broad spectrum of neurodevelopmental disorders." (PMID 41460161, 2026). "Summarizing, this work establishes a C. elegans model of neurodevelopmental disorders caused by GNAO1 mutations." (PMID 34622282, 2022). "We describe a further female patient with GNAO1-associated neonatal-onset epilepsy and a severe neurodevelopmental disorder." (PMID 27072799, 2016). "To date, two main GNAO1-related disorders are reported in OMIM: early infantile-onset epileptic encephalopathy (EIEE17) (MIM#615473) and neurodevelopmental disorder with involuntary movements (NEDIM) (MIM#617493)." (PMID 36003298, 2022). "In conclusion, there is significant overlap in clinical symptoms in the majority of patients, with GNAO1-related neurodevelopmental disorders comprising a continuous spectrum rather than distinct entities." (PMID 40826482, 2025).
neurological disorders (15 papers, 2016 to 2025). "Since the first description of the disease, the number of patients with neurological disorders caused by de novo GNAO1 mutations has rapidly grown up." (PMID 34622282, 2022). "Since 2013, GNAO1-associated neurological disorders have been consistently reported." (PMID 34122306, 2021). "Our findings may go beyond the pediatric neurological disorders caused by mutations in GNAO1." (PMID 38874642, 2024). "As research continues to advance, C. elegans will undoubtedly play a crucial role in unraveling the mysteries of GNAO1-related neurological disorders and improving outcomes for affected individuals." (PMID 40771566, 2025). "GNAO1-dependent pediatric encephalopathy is a recently diagnosed rare yet devastating neurological disease." (PMID 36206333, 2022). "Thus, the neurological disorders are caused by the dominant—and not simple loss-of-function—nature of GNAO1 mutations in human patients." (PMID 34685729, 2021).
tumor (15 papers, 2005 to 2024). "An association had been shown between overexpressed gene GNAO1 and tumor size, tumor differentiation, TNM stage and poor prognosis." (PMID 30987631, 2019). "The nomogram consisting of GNAO1 expression and the tumor-node-metastasis (TNM) model presented good ability in predicting the 3-year relapse for HCC (C-index = 0.614)." (PMID 34900204, 2021). "The IRS of GNAO1 in the tumor was much lower than that in adjacent tissues (t = 9.840, p < 0.001), indicating that the protein expression of GNAO1 was significantly lower in HCC tissues than in adjacent tissues." (PMID 34900204, 2021). "GNAO1 is known as a tumor suppressor gene in some human cancers, and its expression in CMT was downregulated." (PMID 31569550, 2019). "Among cfa-miR-8832 target genes, GNAO1 (guanine nucleotide-binding protein-alpha O1) is known as a tumor suppressor gene in some human cancers and its expression in CMT was downregulated." (PMID 31569550, 2019). "Five potential target genes including STIM1 and GNAO1 were found, and their gene expression was significantly decreased in tumor samples." (PMID 31569550, 2019). "Additionally, G protein subunit alpha O1 (GNAO1), one of the members of Guanine nucleotide-binding protein (G protein), has been recognized to be a tumor suppressor protein whose deregulation can promote carcinogenesis." (PMID 36091786, 2022). "However, statistical evaluation of an effect of methylation status or expression of gene GNAO1 on tumor size and TNM status in our case is impossible, since gene methylation was observed in the majority of samples." (PMID 30987631, 2019). "GNAO1 may act as a tumor suppressor and was a reliable biomarker of relapse prediction for HCC." (PMID 37724126, 2023). "We obtained the protein expression data of Purinergic genes GNAI2, GNAI3, GNAO1, P2RX4, P2RX7, and PANX1 in normal tissues and tumor tissues in the UALCAN database." (PMID 38180750, 2024). "As a tumor suppressor in HCC, the guanine nucleotide-binding protein G(o) subunit alpha (GNAO1) is a m6A downstream target of FTO, and SIRT1-mediated ablation of FTO downregulates GNAO1 mRNA expression through increasing m6A modification." (PMID 37391814, 2023). "The results demonstrated that the GNAO1 related prognostic model can be used to predict HCC relapse within 3 years, and patients with high GNAO1 expression and early tumor stage have a low relapse rate." (PMID 34900204, 2021). "The analysis showed that HCC patients with high GNAO1 expression had better RFS compared to those with low GNAO1 expression, regardless of whether the tumor was at an early or advanced stage." (PMID 34900204, 2021).
cancer (9 papers, 2011 to 2022). A tumor composed of atypical neoplastic, often pleomorphic cells that invade other tissues. "Above all, these results suggest that ESR1, FOXO1, CXCL12, and GNAO1 are involved in the pathogenesis of carcinoma by affecting cell division, complement activation, and protein activation cascades, which support our findings." (PMID 28302149, 2017). "The remaining GNAO1 staining in cancer cells mostly appeared close to the inner side of the cell membrane." (PMID 23984917, 2013). "These associations are likely related to the abnormal GNA15 expression in PDAC cancer cells, whereas GNAL, GNAO1, and GNA14 are preferentially expressed in normal pancreas, which is progressively lost as transformed tissue prevails." (PMID 34290274, 2021). "The second set of three genes, GNAO1, GRIA4 and KCNA5, has been less researched, with only a few studies related to cancer." (PMID 30987631, 2019). "By IHC, we studied and compared the protein levels of GNAO1 in 20 pairs of cancer and adjacent non-cancerous tissues in formalin-fixed and paraffin-embedded tissue slides." (PMID 23984917, 2013).
genetic disease (4 papers, 2022 to 2026). "We collected and reviewed 74 articles (17 for GNB1, 46 for GNAO1, 6 for PDE10A, 2 for PDE2A, and 3 for HCPCA) describing motor, epileptic, and developmental phenotype of patients with genetic disorders of GPCRs–cAMP signaling pathway." (PMID 36003298, 2022).
infection (2 papers, 2022 to 2024). The state of being infected such as from the introduction of a foreign agent such as serum, vaccine, antigenic substance or organism. "Patients with GNAO1 mutations showed exacerbation of hyperkinetic movements with intercurrent infection, heightened emotion, and purposeful movements." (PMID 36054588, 2022). "WB and IHC staining showed that, MAG, a myelin structural protein, was expressed at significantly higher levels in the sciatic nerve of Gnao1-NKD mice than in their controls, and GFP staining again revealed a strong infection efficiency of the virus in injected animals." (PMID 38331815, 2024).
blood neoplasms (1 paper, 2022). "Interestingly, a recent study in human blood neoplasms has also found GNAO1 mutations to activate AKT/ERK/mTOR signaling." (PMID 36003298, 2022).
brain disorder (1 paper, 2025). A disease affecting the brain or part of the brain. "Our study expanded the genotype-phenotype spectrum of GNAO1-related brain disorders." (PMID 40826482, 2025).
GNAO1 also shares sentences with these, for which no sentence is quoted: Choreoathetosis (3 papers); developmental and epileptic encephalopathy, 17 (3); Ataxia (2); Athetosis (2); Cognitive impairment (2); depression (2); infantile epileptic encephalopathy (2); neurodegenerative disease (2); Anxiety (1); autism (1); autism spectrum disorder (1); autosomal dominant hypocalcemia (1); Brain atrophy (1); brain glioma (1); Childhood Encephalopathy (1); colon cancer (1); colorectal cancer (1); congenital heart defects (1); congenital stationary night blindness autosomal dominant 3 (1); deficiencies (1); Dysarthria (1); episodic ataxia (1); Failure to thrive (1); focal dystonia (1); glioblastoma (1); hearing loss (1); Huntington disease (1); hypocalciuric hypercalcemia (1); Hypotonia (1); Hypsarrhythmia (1).
A further 25 diseases each share a sentence with GNAO1 in 1 paper.